CTLA4 (cytotoxic T-lymphocyte associated protein 4)
Diseases named in the same sentence as CTLA4 in open-access papers (continued):
Sharing a sentence is not in itself a finding about the gene and the disease.
endometritis (1 paper, 2022). An acute or chronic, usually bacterial infectious process affecting the endometrium. "In the generalized linear regression model, the diagnosis of cytological endometritis at T20 showed an association with the expression of PD-1 in T lymphocytes (P = 0.02) and a trend with the expression of CTLA-4 in T lymphocytes (P = 0.086) at parturition." (PMID 35937283, 2022). "Thus, we should highlight that our study showed that the levels of PD-1 and CTLA-4 expression in T cells at parturition could predict the occurrence of cytological endometritis in dairy cows, paving the way for the early identification and diagnosis of susceptible cows." (PMID 35937283, 2022). "This may explain, at least in part, the relationship between the expression of CTLA-4 and PD-1 immune checkpoints in T lymphocytes in the prepartum and at partum with endometrial cytology at T20 and T30, an important tool used in the diagnosis of bovine endometritis." (PMID 35937283, 2022).
enterovirus infection (1 paper, 2019). "A few studies have been published on the connection between CTLA-4 and enterovirus infections." (PMID 31401790, 2019).
epilepsy (1 paper, 2025). A brain disorder characterized by episodes of abnormally increased neuronal discharge resulting in transient episodes of sensory or motor neurological dysfunction, or psychic dysfunction. "Abatacept (CTLA-4-Ig), a selective costimulation modulator currently used in autoimmune diseases that functions by blocking T cell activation, shows potential for application in epilepsy cases characterized by immune dysregulation." (PMID 41458814, 2025). "However, robust, replicated datasets demonstrating a stereotyped increase of PD-1, CTLA-4, or lymphocyte activation gene 3 across epilepsy cohorts are still lacking." (PMID 41458814, 2025).
esophageal tumor (1 paper, 2020). "In the following we evaluate differences in expression between therapy-naive tumors compared to the normal tissue and to neoadjuvant pretreated tumors (NACT): As already indicated, CTLA-4 expression is 3.5–4fold increased in esophageal tumor specimen compared to normal tissue." (PMID 31960110, 2020).
fasciolosis (1 paper, 2021). "Altogether, these results suggest that HO-1 activity inhibited by SnPP decreases the production of ROS/RNS during fasciolosis and correlates with an increase of splenic regulatory CD4+ T cells in a process that might involve ICOSL in antigen-presenting cells or CTLA4 expression in Tregs." (PMID 34943041, 2021).
folate deficiency (1 paper, 2021). A nutritional condition produced by a deficiency of FOLIC ACID in the diet. "The WRE sequence of Ctla4 and Edn1 both exhibited decrease in intensity at the Gcm1 peak in folate deficiency." (PMID 33664222, 2021).
follicular adenoma (1 paper, 2024). "One case of follicular adenoma also showed CTLA-4 expression (10% ++)." (PMID 39286684, 2024).
Fulminant hepatitis (1 paper, 2024). Acute hepatitis complicated by acute liver failure with hepatic encephalopathy occurring less than 8 weeks after the onset of jaundice. "The reintroduction of an anti-CTLA-4 antibody in a patient with previous IMH due to an anti-PD-1 treatment is associated with the development of fulminant hepatitis, while the vice versa does not seem to be true." (PMID 38398187, 2024).
gastric cardia adenocarcinoma (1 paper, 2019). A carcinoma that arises from glandular epithelial cells of the cardia of stomach. "A previous study highlighted that the CTLA4 Crs16840252Grs231775Ars3087243Trs733618 haplotype might increase susceptibility to gastric cardia adenocarcinoma, which was similar to the results of the present study." (PMID 31335675, 2019).
goiter (1 paper, 2013). Enlargement of the thyroid gland usually caused by lack of iodine in the diet, hyperthyroidism, or thyroid nodules. "In a previous report, an interaction between the HLA-DRB4 and cytotoxic T-lymphocyte associated antigen 4 (CTLA-4) genes was shown to determine the thyroid function of TPO-positive Japanese HT patients with goiter." (PMID 23522401, 2013).
gout (1 paper, 2023). A condition characterized by painful swelling of the joints, which is caused by deposition of urate crystals. "In this study, we also observed that Tregs produced during gout remission highly expressed CTLA4 and ICOS, which further prompted us to examine the interaction between Tregs and APCs." (PMID 38063198, 2023). "As such, we postulated that an increase in Tregs during gout remission may enhance the suppressive function of Tregs, which is potentially mediated by CTLA4 and ICOS." (PMID 38063198, 2023). "Interestingly, we found that inhibitory genes, such as CTLA4 and inducible costimulator (ICOS), were significantly upregulated during gout remission." (PMID 38063198, 2023).
Headache (1 paper, 2024). Cephalgia, or pain sensed in various parts of the head, not confined to the area of distribution of any nerve. "Headache was more frequent in patients treated with anti-CTLA-4 mono- or combination therapy." (PMID 39135626, 2024).
Hydrocephalus (1 paper, 2025). Hydrocephalus is an active distension of the ventricular system of the brain resulting from inadequate passage of CSF from its point of production within the cerebral ventricles to its point of absorption into the systemic circulation. "Interestingly, the proband showed prominent neurological manifestations, including seizures, hydrocephalus, and demyelination, which are less frequently reported in individuals with pathogenic variants in CTLA4." (PMID 40149457, 2025).
hypertensive encephalopathy (1 paper, 2025). Encephalopathy resulting from hypertension. "Thus, while hypertensive encephalopathy appears to be the most direct cause of the acute neurological event, the presence of CTLA-4 variants may have conferred a predisposing background." (PMID 41346581, 2025).
idiopathic membranous nephropathy (1 paper, 2018). "In a total of 55 patients with biopsy-proven MCD and 26 patients with biopsy-proven idiopathic membranous nephropathy, CD80 and cytotoxic T-lymphocyte antigen-4 (CTLA-4) levels in serum, urine and renal tissue were analyzed." (PMID 30083478, 2018).
idiopathic nephrotic syndrome (1 paper, 2020). Nephrotic syndrome for which no cause has been identified. "CTLA4-Ig abatacept could be a promising regimen for idiopathic nephrotic syndrome." (PMID 32420329, 2020).
Impaired glucose tolerance (1 paper, 2023). "Since higher doses of CsA are associated with impaired glucose tolerance, decreased insulin content, and a decreased β-cell volume, we speculated that combining localized CsA microparticles with other immunomodulatory delivery modalities (i.e., CTLA4-Ig) would potentiate allograft protection." (PMID 37765170, 2023).
infectious mononucleosis (1 paper, 2016). A condition characterized by an increase in mononuclear white blood cells and swollen lymph nodes, which is usually caused by infection with the Epstein-Barr virus. "In addition, since many of the clinical symptoms in infectious mononucleosis are due to an overly exuberant T cell response to EBV-infected B cells, PD-1/CTLA-4 blockade could potentially be more harmful than helpful in such patients." (PMID 27186886, 2016).
Intellectual disability (1 paper, 2018). "Several potentially pathologic genes within the deleted region were of interest including the intellectual disability gene SATB2 and the CD28/CTLA4/ICOS immune gene cluster." (PMID 30087679, 2018).
Interstitial pneumonitis (1 paper, 2025). "In humans with various cancers, the use of immune checkpoint blockade including CTLA4-targeted therapies has been associated with interstitial pneumonitis." (PMID 40100323, 2025).
intracranial aneurysms (1 paper, 2025). "Other previous studies highlight the significance of immune checkpoint molecules, including CTLA-4 and Tim-3, in modulating inflammatory responses in intracranial aneurysms (IA)." (PMID 40943153, 2025).
intracranial hemorrhage (1 paper, 2017). Bleeding within the SKULL, including hemorrhages in the brain and the three membranes of MENINGES. "She later received anti-CTLA-4 monotherapy and developed severe ITP with intracranial hemorrhage." (PMID 28239462, 2017).
ischemia (1 paper, 2012). A hypoperfusion of the BLOOD through an organ or tissue caused by a PATHOLOGIC CONSTRICTION or obstruction of its BLOOD VESSELS, or an absence of BLOOD CIRCULATION. "Blocking the B7-CD28 costimulation pathway by CTLA4 Ig, a recombinant fusion protein, containing the extracellular domain of human CTLA4 (a homologue of CD28), resulting in T cell anergy, ameliorated renal dysfunction and decreased mononuclear cell infiltration in a model of renal cold ischemia." (PMID 24278708, 2012).
Kabuki syndrome (1 paper, 2021). Kabuki syndrome (KS) is a multiple congenital anomaly syndrome characterized by typical facial features, skeletal anomalies, mild to moderate intellectual disability and postnatal growth deficiency. "After the study period closed, expanded PID genetic panels became more widely available, and two of these six patients were later diagnosed with Kabuki syndrome, while a third was diagnosed with CTLA-4 haploinsufficiency." (PMID 33968040, 2021).
Kidney Cyst (1 paper, 2023). Abnormal fluid filled sac within the kidney, either acquired or congenital. "Here, we explored the contribution of 2 immune checkpoints, PD-1|PD-L1 and CTLA-4|CD80/CD86, to kidney cyst growth using different orthologous ADPKD1 models with varying rates of PKD progression." (PMID 37345660, 2023).
laryngeal tumors (1 paper, 2017). "CTLA4 expression was seen mostly in non-laryngeal tumors, while no histological features predicted CTLA4 expression." (PMID 28038471, 2017).
leishmaniasis (1 paper, 2025). Infectious disease that is transmitted through the bite of hematophagous female phlebotomine sand flies. "Additionally, the shared molecular and immunological mechanisms between leishmaniasis and cancer, such as the role of immune checkpoints (e.g., CTLA-4, PD-L1) and pro-inflammatory pathways mediated by TLR signaling, open up novel avenues for therapeutic development." (PMID 41170183, 2025).
leukopenia (1 paper, 2025). "In addition, the Chemo + PD-L1 regimen also showed a higher risk of severe leukopenia compared with the Chemo + CTLA-4 regimen (RR, 3.02; 95%CI, 1.28–7.99)." (PMID 40783512, 2025).
leukoplakia (1 paper, 2024). A white patch or plaque on a mucous membrane that cannot be characterized clinically or pathologically as any other disease. "Finally, we found that NK/T cell subgroups in the HNSCC group highly expressed marker genes of depleted T cells such as CTLA4, LAG3, TIGIT, and HAVCR2, indicating that the inhibition degree of NK/T cells in the HNSCC group was stronger than that of leukoplakia." (PMID 38582791, 2024).
lichen planus (1 paper, 2024). A chronic, recurrent, pruritic inflammatory disorder of unknown etiology that affects the skin and mucus membranes. "Lichen planus/Lichen planus-like eruptions may develop in up to 6% of patients treated with ICIs, more frequently with anti-PD/PD-L1 than anti-CTLA4." (PMID 38611115, 2024).
Listeria infection (1 paper, 2016). "Transient CTLA-4 blockade increased the number of memory CD8+ T cells during low-dose Listeria infection in mice, and CTLA-4 blockade enhanced the response of memory CD8+ T cells." (PMID 27242794, 2016).
lymphatic diseases (1 paper, 2023). "In contrast to PD-1/PD-L1 inhibitors, the CTLA-4 inhibitor exhibits a higher propensity to elicit endocrine diseases, skin and subcutaneous tissue disorders, and gastrointestinal disorders, while displaying a comparatively lower propensity to induce cardiac and hematologic and lymphatic diseases." (PMID 37881181, 2023).
lysosomal disorder (1 paper, 2024). "mTOR pathway mediated autophagic-lysosomal disorder showed significant association with CTLA-4 expression." (PMID 39104530, 2024). "In the future, larger patient sample, clinical intervention research and animal experiment could test the association between CTLA-4 and mTOR pathway mediated autophagic-lysosomal disorder." (PMID 39104530, 2024). "As LC3II was also found to be significantly different, which was a biomarker of mTOR pathway mediated autophagic–lysosomal disorders, we hypothesized that this disorder might be associated with differing expression levels of CTLA-4 on CD4+ lymphocytes." (PMID 39104530, 2024). "The expression of CTLA-4 and its correlation with autophagic–lysosomal disorder should be further studied on CD8+ lymphocytes and NK cells." (PMID 39104530, 2024). "Our study confirmed that CTLA-4 expression on CD4+ cells might also be modulated by mTOR pathway mediated autophagic lysosomal disorder." (PMID 39104530, 2024). "This study was designed to illustrate the association between CTLA-4 expression on CD4+ lymphocytes and the occurrence of SAI and prognosis of patients with SAI, and furthermore to clarify the relationship between mTOR pathway mediated autophagic–lysosomal disorder and CTLA-4 expression." (PMID 39104530, 2024).
macular oedema (1 paper, 2023). "Clinically, subretinal fluid accumulation and macular oedema can occur following anti-CTLA4 treatment, with some patients also experiencing deterioration of visual function." (PMID 37072549, 2023). "In this study, we utilized OCT to examine the emergence of macular oedema during anti-CTLA4 injection; however, no exudative changes were detected in the retinas of experimental mice." (PMID 37072549, 2023).
malignant hypertension (1 paper, 2021). Severe hypertension that is characterized by rapid onset of extremely high blood pressure and hypertension-mediated organ damage. "One might speculate that the enhanced expression of CTLA-4 and CD80 in malignant hypertension could point to an ongoing specific immune response." (PMID 34528115, 2021).
mast cell tumors (1 paper, 2023). "It is worth noting that high expression levels of immune checkpoints, including PD-1, its ligand, and CTLA-4, were observed in neoplastic mast cells, despite limited knowledge on the immunological behavior of mast cell tumors (MCTs)." (PMID 37370399, 2023).
medullary thyroid carcinoma (1 paper, 2023). "In a study on medullary thyroid carcinoma (MTC) in 200 MTC patients, TIM-3 positivity was 48%, and TIM-3 expression was positively correlated with PD-1 and CTLA-4 expression." (PMID 36960057, 2023).
Miosis (1 paper, 2023). Abnormal (non-physiological) constriction of the pupil. "Moreover, the chromosomal locations of CTLA4 and PD-1 are perfect for cross-over during miosis; they are located on the long arm of the second largest human chromosome just above telomeres, giving them ample room to match and cross-over during miosis to create new combinations in the population." (PMID 36661747, 2023).
mucinous tumors (1 paper, 2024). "For example, mucinous tumors displayed a more active immune response compared to the other low-grade carcinomas, with relatively higher levels of CD8 cytotoxic T cells and immune activation marker VISTA, while lower in immune suppressive markers (IDO1, FOXP3, CTLA4)." (PMID 39026018, 2024).
mucormycosis (1 paper, 2022). "PD-1/PD-L1 pathway blockade in a murine mucormycosis model successfully suppressed the targeted molecules and co-suppressed CTLA-4 but led to rapid upregulation of TIM-3 within 4 days of ICI initiation." (PMID 36389687, 2022).
Myalgia (1 paper, 2022). "rs733618 of CTLA4 (additive, p<0.001; CT+TT vs. CC, p=0.011) and rs3181097 of CD28 (additive, p=0.016; GG+AA vs. AA, p=0.036) were associated with myalgia." (PMID 36389676, 2022).
myelofibrosis (1 paper, 2024). A partial or complete replacement of the bone marrow stroma by fibrous tissue. "Collectively, these findings highlight the potential of CTLA-4 inhibition to reinvigorate T-cell-mediated immune responses against malignant cells in myelofibrosis, paving the way for novel therapeutic strategies." (PMID 39682299, 2024).
Myocardial fibrosis (1 paper, 2024). "Masson and Sirius red staining showed that anti‐CTLA‐4 m2a antibody further exacerbated myocardial fibrosis and collagen deposition in the myocardium of EAM mice compared with anti‐IgG antibody‐treated EAM mice." (PMID 38978328, 2024).
myopia (1 paper, 2023). "Many genes related to the immune system have been known to be involved in the development of myopia, for instance, CTLA4 from our analysis involving T cell regulation was found to be uniquely upregulated in LIM, supporting a surge in the expression of several LIM-specific lymphocyte immune pathways." (PMID 38136985, 2023).
neck fracture (1 paper, 2021). "Statistically significant ROR was found for eight, two and one bone AEs respectively with PD‐1, PD‐L1 and CTLA‐4 inhibitors, being pathological fracture (N = 46; ROR = 3.17; LL95%CI = 2.37), spinal compression fracture (42; 2.51; 1.91), and femoral neck fracture (26; 2.38; 1.62) the most common." (PMID 33844854, 2021).
neuroborreliosis (1 paper, 2023). "Thus, although limited by data of a single case, upregulation of CTLA-4 and Ki67 on borrelia-specific T cells may also be indicative of a specific involvement of borrelia, which warrants further study in larger cohorts of patients with neuroborreliosis." (PMID 37880696, 2023).
NK/T-cell lymphoma (1 paper, 2015). "Analysis of 12 single nucleotide polymorphisms (SNPs) in IL-10, TNF-α, lymphotoxin-α (LTA), and CTLA-4 genes was performed for 125 patients with NK/T-cell lymphoma and 300 healthy controls by PCR-ligase detection reactions." (PMID 26108796, 2015). "In this study, our results showed that LTA +252 A > G polymorphism is associated with a 2.9-fold risk of NK/T-cell lymphoma, but other polymorphisms of the IL-10, TNF-α, and CTLA-4 genes are not." (PMID 26108796, 2015).
non-small cell lung adenocarcinoma (1 paper, 2022). Type of epithelial lung cancer arising from glandular origin. "To prove this hypothesis, we studied the combination of anti-CTLA-4 and Pulsed radiation therapy in our 344SQ non-small cell lung adenocarcinoma murine model." (PMID 36275767, 2022).
nutrition disorders (1 paper, 2024). "Conversely, metabolism and nutrition disorders were the most commonly reported delayed irAEs with anti-CTLA-4 medications as opposed to anti-PD-1/anti-PD-L1 medications (ROR025 = 3.13)." (PMID 39588146, 2024).
ocular infection (1 paper, 2021). "We used CD28−/−, CD28−/− CTLA4−/−, and PD-L1−/− mice to determine possible roles of the CD28-CTLA4-PD-L1 axis and their lack of interaction with CD80 in primary ocular infection, eye disease, and latency reactivation following infection with wild-type HSV-1." (PMID 34281386, 2021).
oral mucositis (1 paper, 2018). Inflammation of the mucous membranes of any of the structures in the mouth. "Oral mucositis caused immunotherapy is uncommon but seems more frequent with anti PD-1 inhibitors than with cytotoxic T-lymphocyte-associated antigen 4 (CTLA-4) inhibitors." (PMID 29548299, 2018).
osteomyelitis (1 paper, 2023). An acute or chronic inflammation of the bone and its structures due to infection with pyogenic bacteria. "The high expression of CTLA4 has an important role in immunosuppressive effect in Treg cells; therefore, it is considered as a potential target of osteomyelitis treatment." (PMID 37744377, 2023). "They demonstrated that luteolin, chryseriol, kaempferol, and quercetin are the main active compounds of WWXDD, which are capable for downregulating the percentage of Treg cells via IL-2/STAT5 and suppressing the increased level of Foxp3 and CTLA-4 in osteomyelitis." (PMID 37744377, 2023).